PLA2G6 (phospholipase A2 group VI)
Description:
Calcium-independent phospholipase involved in phospholipid remodeling with implications in cellular membrane homeostasis, mitochondrial integrity and signal transduction. Hydrolyzes the ester bond of the fatty acyl group attached at sn-1 or sn-2 position of phospholipids (phospholipase A1 and A2 activity respectively), producing lysophospholipids that are used in deacylation-reacylation cycles. Hydrolyzes both saturated and unsaturated long fatty acyl chains in various glycerophospholipid classes such as phosphatidylcholines, phosphatidylethanolamines and phosphatidates, with a preference for hydrolysis at sn-2 position. Can further hydrolyze lysophospholipids carrying saturated fatty acyl chains (lysophospholipase activity). Upon oxidative stress, contributes to remodeling of mitochondrial phospholipids in pancreatic beta cells, in a repair mechanism to reduce oxidized lipid content. Preferentially hydrolyzes oxidized polyunsaturated fatty acyl chains from cardiolipins, yielding monolysocardiolipins that can be reacylated with unoxidized fatty acyls to regenerate native cardiolipin species (By similarity). Hydrolyzes oxidized glycerophosphoethanolamines present in pancreatic islets, releasing oxidized polyunsaturated fatty acids such as hydroxyeicosatetraenoates (HETEs) (By similarity). Has thioesterase activity toward fatty-acyl CoA releasing CoA-SH known to facilitate fatty acid transport and beta-oxidation in mitochondria particularly in skeletal muscle. Plays a role in regulation of membrane dynamics and homeostasis. Selectively hydrolyzes sn-2 arachidonoyl group in plasmalogen phospholipids, structural components of lipid rafts and myelin (By similarity). Regulates F-actin polymerization at the pseudopods, which is required for both speed and directionality of MCP1/CCL2-induced monocyte chemotaxis. Targets membrane phospholipids to produce potent lipid signaling messengers. Generates lysophosphatidate (LPA, 1-acyl-glycerol-3-phosphate), which acts via G protein receptors in various cell types (By similarity). Has phospholipase A2 activity toward platelet-activating factor (PAF, 1-O-alkyl-2-acetyl-sn-glycero-3-phosphocholine), likely playing a role in inactivation of this potent pro-inflammatory signaling lipid (By similarity). In response to glucose, amplifies calcium influx in pancreatic beta cells to promote INS secretion (By similarity). [Isoform Ankyrin-iPLA2-1]: Lacks the catalytic domain and may act as a negative regulator of the catalytically active isoforms. [Isoform Ankyrin-iPLA2-2]: Lacks the catalytic domain and may act as a negative regulator of the catalytically active isoforms.
Synonyms: CaI-PLA2; PNPLA9; iPLA2; PARK14; iPLA2beta; NBIA2; GVI; INAD1; IPLA2-VIA; NBIA2A; NBIA2B; PLA2
Tractability: Small molecule: a high-quality ligand is known; it belongs to a druggable protein family. Antibody: UniProt places it where antibodies can reach, with high confidence; its Gene Ontology location is reachable by antibodies, with high confidence; UniProt predicts a signal peptide or a membrane-spanning region; the Human Protein Atlas places it where antibodies can reach. PROTAC: ubiquitination databases record sites on it; a small molecule that binds it is known.
Target class: Enzyme
Gene: Protein-coding gene on chromosome 22 (38,111,495 to 38,214,778, reverse strand). Ensembl gene ENSG00000184381.
Subcellular location: Cytoplasm; Cell membrane; Mitochondrion; Cell projection, pseudopodium
Subcellular location (Human Protein Atlas): Plasma membrane; Microtubules; Nuclear speckles
Pathways (Reactome):
Metabolism: Acyl chain remodeling of CL; Acyl chain remodelling of PC; Acyl chain remodelling of PE
Immune System: Role of phospholipids in phagocytosis
Vesicle-mediated transport: COPI-independent Golgi-to-ER retrograde traffic
Gene Ontology:
Molecular function: identical protein binding; long-chain fatty acyl-CoA hydrolase activity; phosphatidylcholine lysophospholipase activity; phospholipase A2 activity; protein binding; 1-alkyl-2-acetylglycerophosphocholine esterase activity; hydrolase activity; serine hydrolase activity
Biological process: antibacterial humoral response; cardiolipin acyl-chain remodeling; phosphatidylcholine catabolic process; Fc-gamma receptor signaling pathway involved in phagocytosis; phosphatidic acid metabolic process; phosphatidylethanolamine catabolic process; platelet activating factor metabolic process; positive regulation of ceramide biosynthetic process; positive regulation of insulin secretion involved in cellular response to glucose stimulus; lipid metabolic process
Cellular component: cytoplasm; extracellular region; mitochondrion; plasma membrane; cytosol; pseudopodium
Genetic constraint (gnomAD): Loss-of-function variants: 57 observed, 73.13 expected, observed/expected ratio (o/e) 0.78, 90% interval 0.63 to 0.97. The upper end of that interval is the gene's LOEUF score, 0.97, which puts it in group 4 of 6, group 1 being the genes least tolerant of losing a copy. Missense variants: 931 observed, 1,067.4 expected, observed/expected ratio (o/e) 0.87, 90% interval 0.83 to 0.92. Synonymous variants: 413 observed, 433.17 expected, observed/expected ratio (o/e) 0.95, 90% interval 0.88 to 1.03.
Gene-disease validity (ClinGen):
ClinGen rates the evidence that PLA2G6 causes each of these diseases.
PLA2G6-associated neurodegeneration (autosomal recessive): Definitive. Any neurodegeneration with brain iron accumulation in which the cause of the disease is a mutation in the PLA2G6 gene.
Homologues: Orthologues: chimpanzee PLA2G6 (99% identical), macaque PLA2G6 (91% identical), pig PLA2G6 (91% identical), dog PLA2G6 (91% identical), mouse Pla2g6 (90% identical), rat Pla2g6 (90% identical), guinea pig PLA2G6 (84% identical), tropical clawed frog pla2g6 (58% identical), zebrafish pla2g6 (54% identical), rabbit PLA2G6 (51% identical), Drosophila melanogaster iPLA2-VIA (37% identical), Drosophila melanogaster mask (12% identical), and 2 more. Paralogues in human: TONSL (18% identical), NFKBIB (9% identical), NFKBIA (8% identical), ANKRD22 (7% identical).
Diseases named in the same sentence as PLA2G6 in open-access papers:
PLA2G6 is named in the same sentence as 135 diseases in open-access papers, as found by Europe PMC text mining. Sharing a sentence is not in itself a finding about the gene and the disease. The quoted sentences say what the papers report.
Parkinsonism (110 papers, 2010 to 2026). Characteristic neurologic anomaly resulting from degeneration of dopamine-generating cells in the substantia nigra, a region of the midbrain, characterized clinically by shaking, rigidity, slowness of movement and difficulty with walking and gait. "Although much research on this gene has focused on the dopaminergic neurons, whose degeneration leads to clinical parkinsonism, our results highlight the importance of GABAergic neurons to PLA2G6-associated neurodegeneration." (PMID 41404033, 2025). "Since then, loss of PLA2G6 in human patients has been associated also with inherited parkinsonism, as well as with dystonia and ataxia." (PMID 41404033, 2025). "The pathology associated with PLA2G6 mutations, although distinctive in its genetic cause, shares with other neurodegenerative diseases, such as Alzheimer's and Parkinson's, certain key pathogenic mechanisms." (PMID 40717733, 2025). "In the VDAC2 KO cells, the highest magnitude loss was in the protein PLA2G6, a phospholipase, a gene for which loss of function results in a series of infantile neurodevelopmental disorders and Parkinson’s disease." (PMID 40568130, 2025). "The two reported unrelated families with homozygous PLA2G6 mutation had early onset L-dopa-responsive dystonia–parkinsonism, pyramidal signs, and cognitive/psychiatric features, together with mild generalized cerebral atrophy on MRI but no iron accumulation." (PMID 37644186, 2024). "PLA2G6 was also reported recently as the causative gene for PARK14, a form of autosomal recessive early onset dystonia–parkinsonism." (PMID 37644186, 2024). "Further, mutations in PLA2G6 are confirmed as associated with the pathogenesis of numerous neurodegenerative disorders, including Alzheimer’s and Parkinson’s diseases." (PMID 38764027, 2024). "Given that variants in PLA2G6 also cause parkinsonism, we explored if there are defects associated with INAD patient-derived DA neurons." (PMID 36645408, 2023). "In a consanguineous Sudanese family, we identified two variants in PLA2G6 in a compound heterozygous state in two patients with late onset parkinsonism." (PMID 37139542, 2023). "Although both variants were previously reported, these patients had an unusually late onset of disease in the sixth decade of life, expanding the age range of the PLA2G6‐associated parkinsonism." (PMID 37139542, 2023). "Here, we report the case of a young patient with parkinsonism who was homozygous for the p.H479D (c.1435C˃G) mutation in the PLA2G6 gene." (PMID 35329915, 2022). "In conclusion, long-chain fatty acid metabolism-derived metabolites (like oleic acid), xanthine, L-histidine, and phenol are related to the disease severity of PLA2G6 mutation-associated dystonia–parkinsonism (PARK14)." (PMID 36033628, 2022). "A recent review synthesized the clinical and genotypic data available in the literature on parkinsonism with onset in individuals younger than 21 years of age, and it included 16 patients carrying a PLA2G6 mutation." (PMID 35329915, 2022). "PLA2G6-dystonia-parkinsonism (PLAN-DP) is characterized by adult-onset levodopa-responsive parkinsonism with dystonia, and it is associated with several mutations in the PLA2G6 gene." (PMID 35329915, 2022). "Recessive mutations in PLA2G6 cause infantile neuroaxonal dystrophy and atypical neuroaxonal dystrophy, as well as PLA2G6-related dystonia-parkinsonism, also called Parkinson disease 14 (PARK14)." (PMID 35163450, 2022). "This makes the lipid metabolism pathway the most frequently affected pathway in the PLA2G6 mutation-related parkinsonism." (PMID 36033628, 2022). "Phospholipase A2 Group VI (PLA2G6), encoding calcium-independent phospholipase A2, has been isolated as the gene responsible for an autosomal recessive form of early-onset Parkinson’s disease (namely, PARK14)." (PMID 36033628, 2022).
Parkinsonism (continued). "Mutation of PLA2G6 is associated with neurodegenerative disorders in humans, such as autosomal recessive neuroaxonal dystrophy and early-onset parkinsonism in humans." (PMID 35795234, 2022). "Patients with homozygous mutations in PLA2G6 show young onset, progressive cognitive decline, and dopa-responsive dystonia-parkinsonism." (PMID 34299248, 2021). "Biallelic mutations in PLA2G6 (phospholipase A2, group 6, MIM*603604) cause an early-onset dystonia-Parkinsonism (PARK14, MIM#612953) with variable age at onset (10–30 years)." (PMID 34630269, 2021). "Variants in PLA2G6 are known to be associated with autosomal recessive early-onset forms of neurodegeneration, such as infantile neuroaxonal dystrophy 1 or Parkinson disease 14 (OMIM 603604)." (PMID 33159255, 2021). "Mutations in PLA2G6 have been proven to lead to mitochondrial dysfunction and related neurological diseases, including Parkinson’s disease 14 and hereditary spastic paraplegia." (PMID 34207793, 2021). "A genetic analysis with a targeted NGS panel, covering 40 genes associated with parkinsonism, identified a homozygous c.991G > T (p.D331Y) mutation in PLA2G6." (PMID 32183746, 2020). "Accordingly, PLA2G6 mutations lead to the pathogenesis of infantile neuroaxonal dystrophy and PARK14-linked Parkinson’s disease." (PMID 32957701, 2020). "Introduction of the mitochondria-ER contact site-resident protein C19orf12, another causal gene for Parkinson’s disease, in PLA2G6-deficient flies rescues the phenotypes associated with altered lipid composition, ER stress, and neurodegeneration." (PMID 33086624, 2020). "Consistently, homozygous mutations in the iPla2β or PLA2G6 gene have been reported in patients with dystonia-parkinsonism and neuroaxonal dystrophy." (PMID 31409057, 2019). "Mutations in pleiotropic lipid regulators involved in sphingolipid and glycerophospholipid metabolism, PLA2G6, have been found to cause levodopa-responsive parkinsonism with dystonia." (PMID 31031582, 2019). "In recent years, the PLA2G6 mutation was found to be closely related to sporadic early-onset parkinsonism (EOP)." (PMID 30619057, 2018). "PLA2G6 is not only involved in the pathogenesis of PARK14-linked parkinsonism but also in idiopathic PD." (PMID 29108286, 2017). "Mutations in the gene encoding Ca2+-independent phospholipase A2 group 6 (PLA2G6) cause the recessive familial type 14 of Parkinson’s disease (PARK14)." (PMID 29108286, 2017). "This was supported pathologically by the widespread Lewy body presence that is most pronounced in the neocortex documented in postmortem analysis of patients with PLA2G6 mutations and clinically by the presence of Parkinsonism features." (PMID 27268037, 2016). "In conclusion, we described a homozygous p.R741Q mutation in PLA2G6 in 3 affected individuals from two families with clinical features resembling dystonia-parkinsonism." (PMID 27268037, 2016). "Here we report on the clinical and neuroimaging findings of patients from two different families presenting with early-onset Parkinsonism in whom the reported PLA2G6 mutation (c.2222G > A; p.R741Q) was detected." (PMID 27268037, 2016). "Rare forms of PLA2G6-associated dystonia-parkinsonism have been also identified, characterized by sub acute onset in early adulthood, frequently with neuropsychiatric changes and gait disturbance." (PMID 24847269, 2014). "We have recently demonstrated clinical heterogeneity in patients with mutations in the PLA2G6 gene by identifying a poorly defined subgroup of patients who present late with dystonia and parkinsonism." (PMID 20619503, 2012). "The finding of patients with PLA2G6 mutations and L-dopa responsive adult onset dystonia-parkinsonism adds a later onset subgroup to the NBIA clinical spectrum." (PMID 20619503, 2012).
Parkinsonism (continued). "The Lewy bodies in the cases reported here with L-dopa responsive parkinsonian features and the reported cases with dystonia and parkinsonism clearly represent a link between cases with PLA2G6 mutations and Parkinson's disease." (PMID 20619503, 2012). "Cases of dystonia-parkinsonism associated with mutations in PLA2G6 have been reported in Iran." (PMID 40717733, 2025). "Similarly, a splice acceptor variant (NM_003560:c.1078-2 A > G) in PLA2G6, an autosomal recessive gene linked to Parkinson diseases and neurodegeneration, was detected in five heterozygous macaques." (PMID 38969634, 2024). "Two heterozygous variants in PLA2G6 (NM_003560.4:c.2070_2072del (p.Val691del) and NM_003560.4: c.956C>T (p.Thr319Met)) were found in both siblings (Patient 1 and Patient 2) showing late onset parkinsonism." (PMID 37139542, 2023). "Variants in the PLA2G6 gene contribute to an autosomal recessive young onset Parkinsonian syndrome (Park14), Parkinson’s disease, and may even predispose to iatrogenic parkinsonism." (PMID 38028602, 2023). "While parkinsonism is a well-recognized and common side effect of antipsychotic treatment, we speculate that the p.Asp377Tyr variant in the PLA2G6 gene, which lies close to the antipsychotic binding site may influence binding of ligands." (PMID 38028602, 2023). "The appearance of neuropsychiatric symptoms like depression, anxiety or personality changes prior to a diagnosis of parkinsonism in younger individuals might suggest the presence of PLA2G6 gene mutations." (PMID 35329915, 2022). "Interestingly, our data showed that CPEB1 knockdown significantly increased the mRNA levels of Pla2g6, which has been identified as the causative gene for an autosomal recessive form of Parkinson’s disease." (PMID 35496917, 2022). "Cerebellar abnormalities may be a marker for diagnosis and evaluation of PLA2G6 mutation Parkinsonism." (PMID 31496990, 2019). "In 2010, for the first time, the PLA2G6 gene mutation was associated with parkinsonism." (PMID 30619057, 2018). "It has been found that various mutations in PLA2G6 are associated with Parkinson disease 14 (PARK14, MIM:612,953), autosomal recessive form of INAD1(MIM:256600), Neurodegeneration with brain iron accumulation 2A (NBIA2A, MIM: 256,600) and 2B (NBIA2B, MIM: 610,217)." (PMID 28821231, 2017). "Defining the penetrance of PLA2G6 mutations in PARK14-linked Parkinsonism patients is complicated by the age of onset, that can vary widely among patients (8–37 years) and within families, which could lead to pseudo-incomplete penetrance." (PMID 27268037, 2016). "Recessive mutations in PLA2G6 have been associated with different neurodegenerative disorders, including infantile neuroaxonal dystrophy, neurodegeneration with brain iron accumulation and more recently, early-onset dystonia parkinsonism." (PMID 27268037, 2016). "The autosomal recessive transmission of this mutation, as demonstrated by the genotypes and pedigrees, is consistent with the first report of this mutation in a Pakistani/Indian family and with other reports on different PLA2G6 mutations in PARK14-linked Parkinsonism patients from other populations." (PMID 27268037, 2016). "PLA2g6 regulates store-operated Ca2+ entry and is linked to Parkinson's disease." (PMID 26755131, 2016). "In patients with PARK14 early onset dystonia-parkinsonism (< 30 years), PLA2G6 mutations may be identified in up to 6.9%." (PMID 24745848, 2014). "In atypical NAD difficult neuropsychiatric features may evolve, a feature also observed in the third NBIA, PLA2G6 phenotype-PARK14-linked parkinsonism." (PMID 24745848, 2014). "It was hypothesized that mutations causing the dystonia-parkinsonism phenotype may be linked to abnormal regulation of PLA2G6 function and consequent activation of apoptotic pathways." (PMID 23814539, 2013).